NT5C3A (5'-nucleotidase, cytosolic IIIA)
Description:
Nucleotidase which shows specific activity towards cytidine monophosphate (CMP) and 7-methylguanosine monophosphate (m(7)GMP). CMP seems to be the preferred substrate.
Synonyms: cN-III; P5'N-1; P5N-1; PN-I; NT5C3; UMPH1; PSN1; UMPH; p36; POMP; hUMP1; CNSHA8
Tractability: Small molecule: it has a high-quality binding pocket. PROTAC: ubiquitination databases record sites on it; its protein half-life has been measured.
Gene: Protein-coding gene on chromosome 7 (33,014,113 to 33,062,824, reverse strand). Ensembl gene ENSG00000122643.
Subcellular location: Cytoplasm; Endoplasmic reticulum (Isoform 2)
Subcellular location (Human Protein Atlas): Cytosol; Endoplasmic reticulum; Nuclear bodies; Nucleoplasm
Pathways (Reactome):
Metabolism: Pyrimidine catabolism
Gene Ontology:
Molecular function: 5'-nucleotidase activity; protein binding; magnesium ion binding; tRNA 2'-phosphotransferase activity
Biological process: CMP catabolic process; dCMP catabolic process; defense response to virus; dTMP catabolic process; dUMP catabolic process; UMP catabolic process; pyrimidine nucleoside metabolic process
Cellular component: cytoplasm; cytosol; endoplasmic reticulum; mitochondrion
Genetic constraint (gnomAD): Loss-of-function variants: 12 observed, 17.1 expected, observed/expected ratio (o/e) 0.7, 90% interval 0.45 to 1.14. The upper end of that interval is the gene's LOEUF score, 1.14, which puts it in group 4 of 6, group 1 being the genes least tolerant of losing a copy. Missense variants: 191 observed, 218.03 expected, observed/expected ratio (o/e) 0.88, 90% interval 0.78 to 0.99. Synonymous variants: 82 observed, 80.52 expected, observed/expected ratio (o/e) 1.02, 90% interval 0.85 to 1.22.
Homologues: Orthologues: chimpanzee NT5C3A (100% identical), mouse Nt5c3 (94% identical), rat Nt5c3a (94% identical), dog NT5C3A (92% identical), guinea pig NT5C3A (92% identical), pig NT5C3A (92% identical), rabbit NT5C3A (83% identical), zebrafish nt5c3a (80% identical), macaque NT5C3A (75% identical), tropical clawed frog nt5c3a (69% identical), Caenorhabditis elegans F25B5.3 (35% identical), Drosophila melanogaster cN-IIIB (34% identical), and 1 more. Paralogues in human: NT5C3B (50% identical).
Diseases named in the same sentence as NT5C3A in open-access papers:
NT5C3A is named in the same sentence as 22 diseases in open-access papers, as found by Europe PMC text mining. Sharing a sentence is not in itself a finding about the gene and the disease. The quoted sentences say what the papers report.
lung carcinoma (2 papers, 2020). "Although several of the selected early‐stage ADC‐specific proteins have been reported to play a role in tumorigenesis in various cancer types, EDC3 and NT5C3A have not been implicated in lung cancer." (PMID 32536039, 2020).
Ataxia (1 paper, 2021). Ataxia refers to impaired coordination of voluntary muscle movement. "NT5C3A functions as a negative feedback regulator of inflammatory cytokine signaling, but when 5-nucleotidase activity is excessive, it results in a syndrome characterized by ataxia, hyperactivity, short attention span and poor social interaction." (PMID 34987469, 2021).
NT5C3A also shares sentences with these, for which no sentence is quoted: pancreatic cancer (13 papers); cancer (9); tumor (9); Alzheimer disease (2); breast carcinoma (2); glioblastoma (2); infection (2); atherosclerosis (1); breast adenocarcinoma (1); cervix cancer (1); COVID-19 (1); head and neck cancer (1); hemoglobinopathies (1); Miller Fisher syndrome (1); neuroblastoma (1); ophthalmoplegia (1); papillary adenocarcinoma (1); ptosis (1); uterus cancer (1); viral infection (1).